HSF1 (heat shock transcription factor 1)
Diseases named in the same sentence as HSF1 in open-access papers (continued):
Sharing a sentence is not in itself a finding about the gene and the disease.
cancer (continued). "By specifically disrupting the HSF1-mediated stress response in these tumors, HSF1 inhibitors may provide a novel approach to sensitize these cancers to existing therapies and improve clinical outcomes." (PMID 39850800, 2024). "HSF1 activation in cancers thus is not only in response to different stresses but also through a wide array of other mechanisms, including those driven by oncogenic signaling and those that elevate HSF1 expression levels." (PMID 39850800, 2024). "Notably, combining HSF1-targeted cancer therapy with other chemotherapeutic agents and treatment strategies has become an effective oncology strategy and has been initially validated in several studies." (PMID 39261452, 2024). "HSF1 is overexpressed and/or activated in various cancers and may mediate resistance of cancer cells of different histogenesis to various types of anticancer therapies." (PMID 38280079, 2024). "Furthermore, HSF1-KO prevented tissue hyperplasia and cancer development in a mouse mammary gland-specific HSF1-KO model." (PMID 38589452, 2024). "Although, overexpression of heat shock factor 1 (HSF1) is associated with treatment resistance and poor prognosis in many cancers, HSF1 has not been implicated in antiestrogen resistance prior to this recent study." (PMID 38567308, 2024). "Targeting HSF1 in KRAS-mutant cancers, such as PDAC and NSCLC, where chemoresistance is common and therapeutic options are limited could open new avenues for treatment." (PMID 39850800, 2024). "We have summarized recent studies and the current mechanisms on the role of HSF1 in driving chemoresistance, which may provide new avenues for targeting HSF1 in various cancers." (PMID 39850800, 2024). "Consequently, HSF‐1 has garnered significant attention as a promising therapeutic target for various cancer types, with HSF‐1 inhibitors holding promise as potential antitumor agents, increasing the efficacy of HSP90 inhibitors." (PMID 38283176, 2024). "Therefore, activation of HSF1 can be considered a “cancer trait” and a biomarker of tumor aggressiveness." (PMID 39243039, 2024). "Generally, cancer cells exhibit elevated levels of HSF1 expression." (PMID 38748048, 2024). "Therefore, blocking or silencing the HSR by targeting HSF1 or Hsps can be an effective way to reverse thermotolerance in cancer cells." (PMID 38589452, 2024). "Therefore, HSF1 represents a promising target for KRAS-mutant cancers, potentially addressing some resistance mechanisms by disrupting cancer cell stress responses." (PMID 39850800, 2024). "Deletion of HSF1 has been reported to suppress the development of breast and other tumors, including pancreatic tumors and tumors of the digestive system, and is considered a cancer biomarker and an attractive molecular target." (PMID 38567308, 2024). "However, ERK can also directly phosphorylate HSF1 at S326, activating it and promoting drug resistance of cancer cells." (PMID 39682216, 2024). "By targeting HSF1, it may be possible to exploit this stress vulnerability, making KRAS-mutant cancer cells more susceptible to therapeutic intervention." (PMID 39850800, 2024). "Thus, inhibition of proteostasis in cancer cells by targeting HSF1 is a promising anticancer therapeutic strategy." (PMID 38474017, 2024). "Cancer cells are characterized by high expression levels of HSF1." (PMID 39682216, 2024). "HSF1 dysfunction has been shown to inhibit cancer progression." (PMID 38956273, 2024). "HSF1 knockdown sensitized transduced cancer cells to mEHT and reduced tumor growth." (PMID 38589452, 2024). "Therefore, agents capable of repressing the expression of HSP chaperones, like HSF1 inhibitors, are of particular interest for cancer therapy, as many tumors are known to highly rely on the chaperonic apparatus and express elevated levels of HSPs." (PMID 39682216, 2024).
cancer (continued). "HSF1 promotes cancer progression by orchestrating a range of essential cellular processes." (PMID 39690143, 2024). "CsA, an immunosuppressant, enhances the phosphorylation of the negative activator site on HSF1, causing the death of HeLa cancer cells." (PMID 39433125, 2024). "It was demonstrated that HSF1 activation by mTOR (mammalian target of rapamycin) leads to higher expression of cancer stem-like cell markers by activating DNAJB8, which, in turn, enhances the expression of Sox2 in renal carcinoma cells under stressful conditions." (PMID 39682216, 2024). "Intriguingly, HSF1 showed extensive copy number amplification in all cancer types." (PMID 39248163, 2024). "This marks a significant milestone in HSF1-targeted cancer therapy." (PMID 39850800, 2024). "Therefore, the present data imply the pathogenetic relevance of HSF1 in iCCA, affecting the cancer cell compartment and the tumor microenvironment." (PMID 39243039, 2024). "Besides this general activation of HSF1, cancer cells can constitutively activate HSF1, thus allowing its cytoprotective effect through various mechanisms." (PMID 39850800, 2024). "Additionally, HSF1’s role in tumorigenesis is complex, involving multiple signaling pathways that vary across different cancer types." (PMID 39850800, 2024). "HSF1 could assist cancer cells to survive and evade programmed cell death, which leads to enhanced oncogenesis and tumor progression 5, 6, 15-17." (PMID 37153737, 2023). "Further, HSF1 involves multiple layers of cellular regulations to promote malignant phenotypes in cancer cells, including increasing glycolysis to overcome therapy resistance via lactate dehydrogenase A (LDH-A) and promoting autophagy to enhance cell survival via autophagy-related protein 7 (ATG7)." (PMID 37958341, 2023). "In diverse cancers, HSF1 upregulation correlates with the expression of immune checkpoint proteins, which might contribute to poor prognosis and immunotherapy resistance." (PMID 37153737, 2023). "This further adds traction to our hypothesis that pharmacological inhibition of HSF1 in combination with DYRK2 inhibitors could induce enhanced cytotoxicity in cancer cells while also sensitise bortezomib-resistant cells." (PMID 36622366, 2023). "HSF1 inhibition has emerged as a possible cancer therapeutic method." (PMID 37958341, 2023). "In addition, the overlapping expression of DYRK2 and HSF1 was observed across all cancers in TCGA database." (PMID 37886981, 2023). "Due to its complex mechanism, HSF1 plays different roles in various cancer types." (PMID 37958341, 2023). "This suggests that HSF1 may be more effective in controlling cancer cells than the estrogen receptor pathway." (PMID 37958341, 2023). "For example, upregulation of heat shock factor 1 (HSF1), Yes-associated protein 1 (YAP1), Stromelysin 1 and stromal-derived exosomes have emerged as mediators of cancer progression through enhancing cancer cell motility, invasion, metabolic reprogramming and inducing cancer stem cell features." (PMID 35642343, 2023). "HSF1 is an established tumor-promoting signaling factor that is involved in cancer cell migration, and therefore HSF1 driving SMC migration into the lumen may also contribute to MMD lesions." (PMID 37937642, 2023). "HSF1 plays an important role in both cancer cells and normal cells under stress." (PMID 37153737, 2023). "In addition, we explored further the potential values of targeting the HSF1-APOJ-STAT3 axis against CD8+ T cells-mediated cancer cells cytotoxicity." (PMID 36482717, 2023). "HSF1 inhibition has emerged as a possible therapeutic strategy in cancer treatment." (PMID 37958341, 2023). "Furthermore, we discuss the potential of novel therapeutic agents, specifically HSF1 inhibitors, for cancer treatment." (PMID 37958341, 2023). "In addition, we discuss advancements towards the development of HSF1 inhibitors for cancer treatment." (PMID 37153737, 2023).
cancer (continued). "We postulate that HSF1 may be involved in the remodeling of the mammary gland architecture over the female lifetime, as well as the acquisition of invasive cancer cell phenotype." (PMID 37894333, 2023). "Understanding the role of HSF1 and HSPs in ferroptotic cell death can be employed by developing therapeutic interventions for ferroptosis occurrence in a number of pathological conditions, particularly cancer." (PMID 36976734, 2023). "Furthermore, HSF1 has been shown to regulate the expression of several anti-apoptotic genes, including Bcl-2, which can protect cancer cells from radiation-induced apoptosis." (PMID 37958341, 2023). "Intriguingly, expressions of DYRK2 and HSF1 seemed to be either significantly coup-regulated or codown-regulated in response to standard-of-care clinical chemotherapeutic combination regimens across diverse cancers." (PMID 36622366, 2023). "It has been suggested that HSF1 plays an important role in the death of tumor, and it has been reported that HSF1 can regulate the characteristic change of metabolic flux of glycolysis of cancer cells in vivo, so the inhibition of HSF1 activity leads slower proliferation and death of tumor cells." (PMID 37686660, 2023). "The mechanisms behind HSF1-induced tumorigenesis are complex and cancer type-dependent." (PMID 37958341, 2023). "Overexpression of HSF1 leads to radiotherapy resistance in cancer cells." (PMID 37958341, 2023). "Therefore, it is possible that HSF1 promotes cancer cell survival by promoting mitochondrial and metabolic remodeling, or that altered mitochondrial activity promotes HSF1 activity in cancer." (PMID 38164224, 2023). "Not surprisingly, new molecular mechanisms underlying the functions of HSF1 have been continuously discovered, which provide strong evidence to support the notion that HSF1 may serve as an excellent target for novel cancer treatment strategies." (PMID 37153737, 2023). "HSF1 has been reported to be involved in stress-induced cancer cell proliferation via IER5." (PMID 36900163, 2023). "However, recent studies discovered that, in addition to cytoprotective properties, continuous activation of HSF1 increases cell proliferation and survival and reprograms cell metabolism, similar to cancer cells." (PMID 37958341, 2023). "This shows that high levels of HSF1 can regulate several steps of the invasion cascade in cancer cells, which is not necessarily linked to the acquisition of the CD44pos/CD24neg phenotype." (PMID 37894333, 2023). "In conclusion, HSF1 inhibitors have enormous potential as a novel approach to cancer treatment." (PMID 37958341, 2023). "In addition to chemoresistance, HSF1 also plays a role in protecting cancer cells from the effects of radiotherapy by boosting the expression of HSPs." (PMID 37958341, 2023). "To further consolidate this, we explored multiple databases to understand whether DYRK2 and HSF1 expression correlate across diverse cancer datasets." (PMID 36622366, 2023). "This is followed by phosphorylation of AKT and HSF1, leading to cancer stem-like traits." (PMID 37153737, 2023). "Moreover, we saw a positive correlation (Spearman coefficient R=0.33) between DYRK2 and HSF1 expression across all cancers in TCGA database." (PMID 36622366, 2023). "However, the influence of HSF1 on cell plasticity highlights its role in breast morphogenesis and cancer development." (PMID 37894333, 2023). "HSF1 plays an important role in the progression of various cancer types, including those of the breast, lung, ovary, endometrium, and prostate and many other cancers." (PMID 37958341, 2023). "The pyruvate dehydrogenase kinase 3 gene is another target for HSF1, which inhibits the conversion of glucose to Acetyl CoA by inactivating the pyruvate dehydrogenase complex, thus ensuring the continuation of glycolysis in cancer cells." (PMID 35990198, 2022). "Overexpression of HSF1 in tumor tissues is correlated with a worse prognosis in cancer patients." (PMID 35938032, 2022).
cancer (continued). "On the protein level, malignant tumors express HSF1 more abundantly than benign ovarian tumors." (PMID 35311075, 2022). "Furthermore, the reduced OXPHOS activity in HSF1-ablated LSCs, as well as the multitude of other functions driven by HSF1 that support cancer cell proliferation and survival, points to HSF1 inhibition as a potential therapeutic alternative in AML." (PMID 36245043, 2022). "Generally, elevated expression of HSF1 has been described in various cancer types." (PMID 36069792, 2022). "HSF1 plays a vital role in cancer development and indicates poor cancer prognosis." (PMID 36339263, 2022). "HSF1 can promote cancer initiation and progression, which has been proven by numerous studies." (PMID 35606363, 2022). "As a mitotic regulator, HSF1 is a major contributor to cancer morbidity." (PMID 36557005, 2022). "Moreover, in a study of 105 patients with NSCLC, 42.9% of tissue samples exhibited a high nuclear abundance of HSF1, correlating with poor overall survival, cancer stage and nodal metastasis." (PMID 35311075, 2022). "Moreover, genetic knockdown studies of HSF1 have validated the targeted effects in cancers, suggesting HSF1 as a potential therapeutic target." (PMID 35928554, 2022). "Moreover, activation of HSF1-dependent chaperones (e.g., Hsp70, Hsp40, and Hsp27) participates in cancer cell growth and survival." (PMID 36009046, 2022). "Consistent with its oncogenic roles, HSF1 is highly expressed in a variety of cancers." (PMID 35180892, 2022). "This suggests that the transcriptional regulatory network generated during heat shock and dependent on HSF1 may be differently regulated in the analyzed cancer types." (PMID 36010586, 2022). "We assume that the observed differences between cancers may result from various posttranslational modifications of HSF1, its protein partners, and chromatin organization in target genes." (PMID 36010586, 2022). "For instance, high levels of HSF1 correlate with poor prognosis in cancer patients." (PMID 35485710, 2022). "However, differences between the analyzed cancer types were noted in the regulation of HSF1-dependent genes, indicating the presence of cell-type-specific mechanisms." (PMID 36010586, 2022). "Actually, loss of either HSF1 or HSF2 in cell experiments showed that these cells result in a dysregulated response to nutrient stresses in vitro and that tumor progression was reduced in cancer cell line xenografts." (PMID 36430241, 2022). "In particular, HSF1 is well known to be hyperactivated in several cancer types." (PMID 35080342, 2022). "Different from the heat shock response, HSF1 could drive a transcriptional program to endorse the malignant phenotype of cancer cells." (PMID 35006040, 2022). "In other words, elevated expression of HSF1 has been observed with a poor prognosis of cancer." (PMID 35990198, 2022). "Other potential contributing factors are the accumulation of the mutant cancer proteome and rapid proliferation of cancer cells, which may select for increased levels and activity of HSF1 via additional mechanisms." (PMID 36245043, 2022). "SCENIC analysis showed that heat shock factor 1 (HSF1), which maintains proteostasis in response to stress environments by inducing the expression of heat shock proteins, was significantly upregulated in cancer cells." (PMID 35967424, 2022). "Previous research on HSP expression from both the stress response and cancer fields involves HSF1." (PMID 36069792, 2022). "Regarding the correlation between a high level of HSF1 and the deterioration of disease in the initiation, promotion, and progression of cancer, HSF1 could act as a potential therapeutic target." (PMID 35938032, 2022). "HSF1, localized to chromosome 8q24.3, prevents cancer cell death when exposed to stressors, which indispensable for various malignant transformation–related signaling pathways, thereby facilitating cancer cell proliferation and migration and affecting the tumor microenvironment." (PMID 36069792, 2022).
cancer (continued). "In addition, our previous study revealed the mechanism by which cyclosporin A suppresses cancer progression by inhibiting HSF1 activity." (PMID 35180892, 2022). "Indeed, cancer cells adopt HSF1, UPR, mtUPR, and auto/mitophagy as proteotoxic stress responses to survive protein aggregation." (PMID 36601538, 2022). "Elevated HSF1 activity in multiple cancer types is a frequent occurrence." (PMID 35080342, 2022). "Our results indicate that the use of an inhibitor of HSF1 activity in combination with an autophagy inhibitor results in effective cancer cell death, therefore, this therapeutic approach may be a promising treatment regimen for certain patients." (PMID 35893747, 2022). "We recognized that both the GSDMD and HSF1 genes are 889.264 kb apart on the same locus on 8q.24 and 15,810.256 kb downstream from one of the most overexpressed oncogenes in human cancer, the MYC chr8 (127735434-127742951)." (PMID 36497066, 2022). "HSF1 is a chaperone that associates with both HSP70 and HSP90, and it has been shown to play a significant role in different cancers based on its functions in supporting cell migration, invasion, proliferation, and cancer cell metabolism." (PMID 35928554, 2022). "Moreover, HSF1 controls the transcriptional program of other genes that support highly malignant human cancers, which makes its suppression even more attractive." (PMID 35893747, 2022). "HSF1 fosters cancer cell to grow independently of growth signals." (PMID 35311075, 2022). "Targeting mtUPR or HSF1 may be useful to develop therapies that increase aggregation-related stress and apoptosis in cancer while also impeding onco-suppressor aggregation." (PMID 36601538, 2022). "The role of HSF1 in cancer has received widespread attention in recent years." (PMID 35006040, 2022). "Since the acquisition of DNA-binding competency depends on temperature and concentration of HSF1, we assumed that HSF1 may be active in cancers with high levels of HSF1." (PMID 36010586, 2022). "Because cancer cells might have a different propensity to form HSF1 foci, this observation needs to be validated in other models." (PMID 36195608, 2022). "Therefore, our result showing that HSF1 suppression can sensitize cancer cells to anti-mitosis drugs has the potential to inspire improved clinical treatments." (PMID 34922589, 2021). "Heat shock Factor 1 (HSF1) is a master regulator of transcriptional programs linking the translational flux to the metabolic state of the cells and enabling the adaptation to the high anabolic demands of cancer cells." (PMID 34546000, 2021). "HSF1 has been suggested to play a role as a potential prognostic biomarker in other cancers." (PMID 34064083, 2021). "Moreover, post-translational modifications regulate and modulate HSP70 and HSF1 activity in normal and cancer cells." (PMID 34771616, 2021). "We extended our analysis of the role of HSF1 in ferroptosis resistance to other cancer cell types." (PMID 34223704, 2021). "However, the major stress-responsive factor HSF1 appears to support cancer cell growth, survival and metastasis 19,21." (PMID 33390814, 2021). "In contrast, in cancer, high levels of active, nuclear HSF1 support malignancy by coordinating a transcriptional signature partially distinct from heat shock, including targets that regulate cell cycle progression, chaperone production, and repression of apoptotic factors." (PMID 33208463, 2021). "Indeed, the HSF1 pathway represents an attractive therapeutic target as it not only allows cancer cells to survive aneuploidy-induced proteotoxic stress, but it also plays an important role in cancer progression and chemoresistance." (PMID 33268814, 2021).